CD34 (CD34 molecule)
Diseases named in the same sentence as CD34 in open-access papers (continued):
Sharing a sentence is not in itself a finding about the gene and the disease.
tumor (continued). "The expression level of CD34, a surface marker of proliferating vascular endothelial cells, was significantly decreased inside tumor tissue infected by ST/TRAIL-RGD4C-ES compared to other treatment groups." (PMID 35003007, 2021). "In line with impaired M2-like macrophage infiltration, we observed a decrease in CD34+ blood vessels in tumours growing in an IL-1B ablated microenvironment." (PMID 34290237, 2021). "Extremely rare cells, for example, WBCs in cerebrospinal fluid, CD34 (+) cells for stem cell transplantation, and circulating tumor cells (CTCs) for prognosis, can be concentrated and detected at high accuracy and sensitivity." (PMID 34207912, 2021). "In the immunohistochemical study, tumor cells showed positivity for CD34, CD99, and BCL2 and negativity for EMA, protein S100, and glial fibrillary acidic protein." (PMID 34211794, 2021). "IHC staining in tumor specimens with NKX2‐1‐AS1 overexpression revealed enhanced CD34 expression, which was reversed by NKX2‐1‐AS1 knockdown." (PMID 33512745, 2021). "In larger vessels of tumor adjacent lung tissue as well as in normal/healthy lung tissue, CD34 clearly marks the vasculogenic zone, where also CD44‐positive LR‐MSCs reside, which coexpress the MSC marker CD146." (PMID 32830458, 2021). "The tumor (n = 11) and stromal (n = 4) markers were titrated on a mixture of two HGSOC cell lines, two dissociated primary tumor tissues, CD34+ cells, and unstimulated and stimulated healthy PBMCs." (PMID 33670410, 2021). "Two special angiogenesis markers, α-SMA and CD34, in tumor tissues were detected after ERRAC treatment." (PMID 34476005, 2021). "The IHC results demonstrated that the staining of HIF-1α, VEGF and CD34 proteins in xenograft tumor tissues from nude mice administrated with ASP (HASP, MASP and LASP) was significantly weaker compared with the PBS group." (PMID 34093799, 2021). "The tumor tissue was stained with Sirius red, CD34, and CK19 to evaluate fibrosis, microvascular density (MVD), and tumor cell density." (PMID 34249707, 2021). "This origin is reinforced mainly by the same location and arrangement of stromal cells in the tumour as CD34+SCs/TCs in the normal breast." (PMID 33916213, 2021). "CD44 was proved to be a marker of BC progression and stem-cell properties, and CD34 can promote tumor vascular endothelial cell proliferation, tumor invasion, and metastasis." (PMID 37305162, 2021). "Apart from its sensitivity in identifying DFSP, WT1 is very helpful in distinguishing recurrent/residual tumor cells from fibroblasts/myofibroblasts of scar tissue after surgical excision, which can share CD34 immunostaining with the cells of DFSP." (PMID 33445443, 2021). "In blood vessels close by and within NSCLC areas CD34(+) EPCs were found less frequently within the vessel wall but more in tumor region, strongly confirming their role in tumor vascularization." (PMID 32830458, 2021). "We used antibodies against the vascular endothelial markers CD31 and CD34 to detect blood vessels and observed less but bigger vessels in the tumor areas as compared to the surrounding brain parenchyma." (PMID 33435218, 2021). "They found that vessels that encapsulate tumor clusters (VETC) pattern, which is characterized by the presence of CD34+ vessels completely encapsulating tumor clusters of HCCs, corresponds to rapid tumor dissemination and high recurrence rates." (PMID 34201284, 2021). "CD34 was used to label the endothelial cells in tumor tissues and determine the microvascular density." (PMID 34815366, 2021). "On d 4, the tumor blood vessels were reduced, which was validated by a CD34 immunohistochemical stain, confirming the presence of focal necrosis and irregular foci of hemorrhage in the tumor tissue." (PMID 35004528, 2021). "We also found that both in the central areas and peritumoural areas of peritoneal tumour tissues, CD34‐labelled vascular density was prominently reduced in si‐Piezo1 group than that in control group." (PMID 33439514, 2021).
tumor (continued). "Semiquantitative analysis showed that the number of cells co-expressing CD34 and αSMA varied depending on the tumour area examined." (PMID 33916213, 2021). "Histopathological indicators (degree of tumor cell differentiation, mitoses, and others) and ER, PR, Her2/neu, Ki-67, and CD34 expression levels were determined." (PMID 34059727, 2021). "CD34 was used to label vascular endothelial cells to reflect the MVD in the tumor tissue of nude mice to assess tumor angiogenesis." (PMID 33442403, 2021). "The numerical density of CD34+ cells in the tumor of the treated group was lower by 72.69% and by 57.57% than in untreated mice by the day 5 and 20 after virotherapy, respectively." (PMID 33806229, 2021). "Immunohistochemistry performed on an independent tissue chip (n=75) revealed significant upregulation of Tagln2 in tumor-derived ECs which were specifically immunolabeled with CD34." (PMID 34150622, 2021). "Further, the tumor didn’t express desmin, ck-pan, α-smooth muscle actin, S-100, myoglobin and CD34, suggesting a dedifferentiated tumor." (PMID 33422117, 2021). "The CD34-marked tumor vessels in circCRIM1-overexpressing tumors were larger and more abundant, while SKP2 expression was obviously higher." (PMID 34869393, 2021). "In the tumor/tumor-like conditions of the skin containing CD34+ stromal cells, these cells can be the neoplastic component or secondary reactive stromal component of tumors of other cell lines." (PMID 34298962, 2021). "Tubes characterized by PAS+CD34− tumor cells within the cavities were considered VM channels (red arrows)." (PMID 33850110, 2021). "Although the immunofluorescence revealed that the number of CD34+α-SMA+ arteries in the tumor area was more than in the contralateral area, the expression of AQP4 in the astrocytes around the vessels was weak in the tumor area." (PMID 35083148, 2021). "The first is associated with CD34-positive stromal fibroblastic/fibrocytic cells (CD34+ SFCs), which synthesize and remodel the extracellular matrix, thereby contributing to tissue repair, fibrosis, and tumor stroma formation." (PMID 34326362, 2021). "This experiment confirmed that the GdECs maintain their tumorigenic potential even after endothelial differentiation and that CD34 expression identifies in vivo the most aggressive tumor cells." (PMID 34253243, 2021). "In support of our findings that IL-1B drives the infiltration of innate immune cells with putative tumour-killing capacity, by inhibiting M2-like macrophages, we found a reduction in CD34+ blood vessels in tumours overexpressing IL-1B." (PMID 34290237, 2021). "MVD was assessed by CD34 immunostaining in tumour (CD34-indexT) or tumour including necrosis (CD34-indexTN)." (PMID 34327591, 2021). "Immunohistochemically, the tumor cells were diffusely positive for vimentin and focally positive for CD34 and alpha-SMA; lipoblasts within the tumor were focally positive for S-100." (PMID 34797454, 2021). "In general, healthy ECs and tumor-derived ECs were positive for all tested markers except for CD34 (VWF+, ACE+, CD31+, CD133+, CD105+), but pathological ECs were characterized by lower levels of expression." (PMID 34445568, 2021). "Apart from lacking E-cadherin, investigators have reported differences in tumor stroma between ILC and IDC tumors, with fewer CD34-positive fibroblasts, lower levels of tumor-infiltrating lymphocytes, and reduced desmoplastic reaction in ILC." (PMID 34697300, 2021). "We used immunophenotyping by multiparameter flow cytometry to examine the effects of APVO436 on tumor burden reflected by CD123+CD34+CD38- target blast cells." (PMID 35096610, 2021). "By IHC of CLDN5, exSFT/HPC revealed well-preserved vascular tight junctions that overlapped with CD34 expression on a background of diffuse immunoreactivity in tumor cells." (PMID 33799999, 2021).
tumor (continued). "Upon development of palpable tumors (day 7 post injection), 5 × 106 CD3+CD34+ cells transduced either following IL-7 culture or CD3 activation were adoptively transferred intravenously into tumor-bearing mice." (PMID 34172810, 2021). "CD34 expression also gradually decreased, implying that human stromal elements are replaced by murine stroma as the tumor was engrafted in the new microenvironment." (PMID 34327143, 2021). "It has been well-demonstrated that EZH1/2 enzymes are involved not only in tumor development and progression, but also in the regulation of normal hematopoiesis from CD34+-HSPC." (PMID 33467134, 2021). "Tumor growth was observed for 10 days after treatment, and then histopathology stains (HE, CD34, and γH2AX) were applied to the tumor samples." (PMID 33547949, 2021). "In both tumor and contralateral areas, data indicated that the number of cluster designation 34 (CD34+) alpha-smooth muscle actin (α-SMA−) veins were more than that of CD34+α-SMA+ arteries." (PMID 35083148, 2021). "High expression of CD34 or high MVD is closely correlated to the tumor progression and poor prognosis." (PMID 34660264, 2021). "Immunohistochemically, the tumor cells were diffusely positive for vimentin and focally positive for CD34 and alpha-SMA; lipoblasts were focally positive for S-100." (PMID 34797454, 2021). "Here we used CD34+ CD45- to sort subpopulations of tumor cells using flow cytometry as the most effective approach towards enriching stem-like tumor cells, thereby eliminating hematopoietic stem cells which are CD34+CD45+." (PMID 34026616, 2021). "Tumor microvessel density (MVD) characterized by CD34 expression was assessed to evaluate the degree of angiogenesis in rapidly growing tumor." (PMID 33685316, 2021). "The ssGSEA analysis of tumor samples with high and low expression of CD34/CD276 showed that the tumor samples with high expression of CD34/CD276 had a higher immune score, and ssGSEA was a single sample GSEA algorithm." (PMID 34307389, 2021). "In contrast, the number of CD34+α-SMA− veins in the tumor area were less than in the contralateral area." (PMID 35083148, 2021). "These tumor cells also exhibited increased levels of CD34, an observation in line with previous reports." (PMID 34359889, 2021). "It is shown that simultaneous assessment of the expression of the CD34 differentiation cluster and the production of IL-18 cytokine by the tumor can also be useful for determining the probability of IC-NST metastasis in RLNs." (PMID 34059727, 2021). "In close proximity to the tumor area, CD34+ cells are mobilized from the adventitia and are recruited to the tumor tissue in the form of cell cords." (PMID 34359889, 2021). "Considering its nearly perfect specific expression in human tumor tissues, the anti-CD34 mAb was also considered a potential candidate." (PMID 32483444, 2020). "In order to assess intra-tumoral microvessel density (IMVD), which reflects tumor angiogenesis, we performed immunohistochemical staining for CD34." (PMID 33233701, 2020). "The number and morphological characteristics of blood vessels in each tumour were assessed by immunohistochemical staining of CD34." (PMID 32303680, 2020). "Conversely, the stromal reaction in nerve components, neuroglial units or certain neoplasms growing in adipose tissue occurs along with the conservation of CD34 expression in TCs/CD34+SCs." (PMID 33353193, 2020). "In the present study, we determined MVD by using specific CD34 antibody to mark endothelial cells in tumour." (PMID 32475087, 2020). "SNU484 was the only tumor showing the heterogeneous enhancement pattern on T2 images with a high level of CD34 expression." (PMID 32293340, 2020). "To summarize, DFSP of the breast is an extremely rare malignancy characterized by spindle tumor cells arranged in a storiform pattern and positivity for CD34." (PMID 33224981, 2020).
tumor (continued). "In vivo, tumor volume and weight were reduced, and the expression of VEGF, EGF, IL-10, TGF-β, and CD34 was suppressed in the tumor microenvironment, while cell apoptosis was induced." (PMID 32595723, 2020). "The strands of TCs/CD34+SCs contained most of the tumour vascularization and their limit with Antony A zone groups was regular or irregular, with some strands of TCs/CD34+SCs penetrating the Schwann cell groups." (PMID 32560571, 2020). "By immunohistochemistry, the tumor cells stained positively for S-100 (focal +), CD34 (strong +++) and Ki-67 (20%), and negatively for smooth muscle actin, pan-cytokeratin, neurofilament, pan-cytokeratin-L, GFAP, CD31, STAT6, ERG, myogenin, and MyoD1." (PMID 32590748, 2020). "A comparative analysis of antibody binding showed that all antibodies, except the anti-CD34 mAbs, were detectable in both human and mouse hepatic sinusoidal and tumor endothelial cells." (PMID 32483444, 2020). "CD34 is often used as a marker for tumor vasculature in cancer studies, and CD34+ cells have been used to characterize vascular patterns within tumor tissues." (PMID 33304925, 2020). "Pre-treatment NLR values and CD34 expression levels in tumor tissue samples were analyzed to explore their association with PSA, Gleason score, and tumor stage." (PMID 32962642, 2020). "Diffuse expression patterns of tumor cells with the anti-CD34 and anti-pan-TRK antibodies were observed in the YWHAE-NTRK3 case by immunostaining." (PMID 32825119, 2020). "The total BrdU-positive rate increased 4-fold in CD34-positive cells in transplanted tumours compared to original tumours." (PMID 33123267, 2020). "We found FMK-MEA significantly inhibits p90RSK phosphorylation in tumor vasculature, as shown by the increased Pearson's correlation between CD34+ cells and phosphorylated-p90RSK+ cells." (PMID 33304925, 2020). "Tumor frequency results showed the predominance of sellar regions and right sphenoid wing in lesions with positive expression of CD34." (PMID 32974148, 2020). "A brown CD-34 stained endothelial cell or groups of endothelial cells that clearly separate from adjacent microvessels, tumor cells or other connective tissue elements, were considered as a single countable microvessel." (PMID 32620162, 2020). "Here, we obtained the MVD values by measuring the positive expression of CD34, because CD34 is a vascular marker factor expressed mainly in neovascular endothelial cells of tumor." (PMID 32831873, 2020). "To confirm increased stem cell gene expression in these hyperplastic regions, we also assessed the mRNA level of Lin28B, CD34, Lgr6, and Sox2, which can serve as markers for stem-like tumor cells in skin squamous cell carcinoma." (PMID 32895364, 2020). "We therefore performed immunofluorescence staining of tumor sections using the angiogenic endothelial cell marker CD34." (PMID 33194619, 2020). "On day 20 of tumor growth, BMPER was highly expressed, while CXCL10, HOXA9 and the tumor blood vessel marker CD34 were lowly expressed." (PMID 32432046, 2020). "Immunohistochemical analysis of the resected tumor revealed that the tumor cells expressed positive results for CD34, vimentin, and Bcl-2, focally positive for cytokeratin AE1/AE3, and weakly positive for STAT6." (PMID 33188464, 2020). "CD34 antigen was used as a marker molecule of the blood vessel in tumor tissues to count blood vessel density." (PMID 33192508, 2020). "Along with further tumor progression, BMPER expression was gradually reduced, while CXCL10 and HOXA9 expression was gradually elevated, which was spatially associated with CD34 expression." (PMID 32432046, 2020). "The expression of CD34 in the drug treatment groups was significantly lower than that in the control group, and the microvessel density in the corresponding tumor tissues was smaller." (PMID 33192508, 2020). "We observed that CD34-positive cells generated tumours more effectively and the tumours grew faster compared to CD34-negative cells." (PMID 33123267, 2020).
tumor (continued). "A high expression of CD34 in tumor tissue indicates intensive tumor neovascularization and increased MVD, which was also shown in this study." (PMID 32962642, 2020). "Consistently, our data indicated that in the UV-induced SCC, both CD34 and slow-cycling BrdU-positive cells only represented a minor fraction (approximately 5%) of the tumour cells." (PMID 33123267, 2020). "Consistent with our previously published data, semiquantitative assessment of the proportion of CD34+ fibroblasts in the tumor stroma of ILC revealed their partial preservation, with pronounced intertumoral heterogeneity." (PMID 32435886, 2020). "A noteworthy relationship was seen in the present study between the compactness of tumor blood vessels in the tissue sample and CD34 expression, which showed disease belligerence." (PMID 33383808, 2020). "In the post-vaccination tumor, the expression of cleaved caspase 3 was co-localized in endothelial cells with CD34-positive staining and Foxp3-positive cells." (PMID 32164575, 2020). "This assumption is indirectly confirmed by the correlation of DCs with a weak expression of CD34 with the fragmentation phenomenon in the tumor solid component (p = 0.001)." (PMID 32849870, 2020). "The advantage of the iPS approach is the donor CD34 + cells are fully autologous with the tumor cells as they are both derived from the same individual." (PMID 32504051, 2020). "Reductions in tumour microvascular density (five patients, based on CD34 staining) and/or decreases in tumour cell proliferation (two patients, based on Ki67 staining) were apparent." (PMID 32741975, 2020). "Next, a tumor spheroid formation test was performed to investigate the tumorigenic ability between CD34-overexpressing PKP+ tumor cells and control cells." (PMID 32586050, 2020). "This strategy discriminates among the total population of cancer cells (SmoM2-YFP+/α6-Integrin+ cells), the CSCs (CD34+ cells), and the somatic cells of the bulk of the tumor (CD34− cells)." (PMID 32197405, 2020). "Later, BMPER was continuously highly expressed, which significantly increased CD34-positive blood vessels in tumor regions." (PMID 32432046, 2020). "Further investigations regarding the effects of CD34-overexpressing PKP+ tumor cells on cell migration included the in vitro cell scratch assays, which were employed to detect their migratory abilities in vitro." (PMID 32586050, 2020). "CD34 staining additionally revealed upregulated expression in glial cells within the tumour in a focal and bushy-like fashion, while the gangliocytes remained negative." (PMID 32049624, 2020). "Similar results were obtained from Western blotting analysis to confirm increased protein expression of CD34 in PKAP+ tumor cells compared to PKP+ cells." (PMID 32586050, 2020). "It was observed that the immunohistochemical expression of CD34 and α-SMA-positive myofibroblasts showed an association with tumor differentiation levels, which indicates an aggressive behavior of OSCC in their presence." (PMID 33383808, 2020). "Next, shRNA lenti viruses were transfected into PKAP+ tumor cells to silence endogenous CD34 expression, and Western blotting was used to detect the efficiency of CD34 knockdown in PKAP+ cells." (PMID 32586050, 2020). "We next immunohistochemically analyzed SEMA3A expression and CD34 expression in the same tumor to evaluate the correlation of SEMA3A with the MVD." (PMID 32842711, 2020). "Then, we will examine tumours of the peripheral nervous system, in which TCs/CD34+SCs have an important role, and in tumour-invaded nerves." (PMID 32560571, 2020). "TPX2 siRNA upregulated the expression of IGFBP-3, resulting in significantly reduced CD34-positive micro vessels in the tumor." (PMID 33033514, 2020). "On immunostaining, the tumor is diffusely and strongly positive for CD34, an antigen in fibroblastic cells, as well as vimentin and Bcl-2." (PMID 31848901, 2020).